MYCN (MYCN proto-oncogene, bHLH transcription factor)
Diseases named in the same sentence as MYCN in open-access papers (continued):
Sharing a sentence is not in itself a finding about the gene and the disease.
tumor (continued). "SRCIN1 expression is a risk factor independent from the other known risk factors, such as MYCN oncogene amplification, INSS stage and age at diagnosis, recognized as the strongest indicators of aggressive tumor behavior in NB patients." (PMID 31285546, 2020). "With the ability to demonstrate the state of amplification heterogeneity of the tumor cells and the nature of amplification units (double-minute chromosomes or homogeneously stained regions), detection of MYCN amplification with FISH remains a reliable method." (PMID 30691436, 2019). "We further unravelled that the DHA synesis enzyme ELOVL2 was remarkably upregulated after MYCN depletion and its tumor suppressive properties in this childhood malignancy both in vitro and in vivo." (PMID 31856871, 2019). "Since AURK was found to bind and stabilization of MYCN, its inhibition resulted in MYCN degradation and reduction in tumor volume in a model of NEPC." (PMID 31627186, 2019). "Through various prioritization strategies, we provide a core set of lincRNAs with a potential role in NB tumor biology, up- or downstream of the key NB driver genes MYCN, ALK and PHOX2B." (PMID 30952905, 2019). "As expected, there were extensive differences in gene expression when comparing the two different tumor types, including 6601 DEGs when comparing EμMyc to Th-MYCN tumors and 6674 DEGs in the EμMyc/Casp2−/− versus Th-MYCN/Casp2−/− tumor comparison." (PMID 30670683, 2019). "LIN28B protein was shown to be an independent risk factor determining a poor outcome in NB, through negative regulation of let-7 miRNA, that leads to a high MYCN protein expression and, therefore, to an aggressive tumor phenotype." (PMID 31575060, 2019). "Three/42 patients (7.1%) with amplified MYCN, who were treated with chemotherapy (n = 1) or tumor resection (n = 2), are alive." (PMID 30634996, 2019). "Multivariate analysis was calculated using multiple logistic regression adjusted for age, gender, grade of tumor differentiation, MYCN status, Shimada histology, serum NSE and urine VMA." (PMID 31619207, 2019). "Mice hemizygotic for both ALKF1174L and MYCN amplification exhibited high tumor penetrance with rapid lethality superior to that observed in MYCN hemizygotes allowing for elucidating the interplay between the ALK and MYCN pathways." (PMID 32903387, 2019). "Of these, 108 DEGs were identified in the Th-MYCN/Casp2−/− versus Th-MYCN tumor comparison and 197 DEGs in the EμMyc/Casp2−/− versus EμMyc tumors (fold change [FC] > 2 and < −2; FDR < 0.05)." (PMID 30670683, 2019). "MYCN-amplified tumor cells exhibit a higher propensity for spheroid formation than non-MYCN-amplified cells." (PMID 32903387, 2019). "Multidimensional scaling plots showed that the EμMyc and Th-MYCN tumor transcriptomes form distinct clusters, highlighting differences in gene expression changes between the two tumor types." (PMID 30670683, 2019). "The amplified MYCN copies are considered the most important marker for the prediction of tumour relapse and progression in NB." (PMID 31511046, 2019). "IMR32 cells show a deletion of the short arm of chromosome 1 (1p) and a MYCN amplification in double minute chromosomes, whereas the SK-N-SH cells represent a stage 4 tumor." (PMID 31861249, 2019). "The treatment algorithm for NB is dependent on risk stratification, which is defined using parameters such as age, disease stage, tumour histopathology, MYCN status and DNA ploidy." (PMID 31088252, 2019). "These histological features were in particular evident in tumor tissue from the MYCN-amplified IMR-32 xenograft." (PMID 30542116, 2019). "MYCN amplified tumours often respond well, in contrast tumours with other genetic modifications such as loss of chromosome 11q do not4, hence the need for additional treatment options for this group." (PMID 31235824, 2019).
tumor (continued). "Out of 536 lincRNAs differentially expressed in MYCN amplified vs MYCN single copy tumor samples, 36 were also perturbed in at least one of two MYCN model systems." (PMID 30952905, 2019). "The COG risk group imports factors such as INSS stage, age of diagnose, MYCN, tumor histology, and DNA ploidy status." (PMID 31338261, 2019). "Mouse xenograft results showed that enforced ELOVL2 expression diminished the promotion effect of MYCN on tumor growth, mass and re-raised the DHA content in tumors." (PMID 31856871, 2019). "From this cohort, the most predictive factors were identified including INRG stage, age, histologic category, grade of differentiation, MYCN status, 11q aberration, and tumor cell ploidy." (PMID 30754710, 2019). "In general, MYCN drives NB tumorigenesis through the induction of several target genes involved in many pathways regulating tumor cell proliferation, growth, apoptosis, energy metabolism, and differentiation." (PMID 31040907, 2019). "MYCN-mediated oncogenic transformation is responsible for aggressive tumour formation and poor prognosis in NB11." (PMID 30914706, 2019). "Although MYCN and tumor cell ploidy are the two biologic markers that have been classically utilized by the COG to assign risk groups, chromosomal aberrations have been identified and used by different groups." (PMID 30754710, 2019). "Consistent with a tumor progression function, we found higher expression of Megf6 in EμMyc/Casp2−/− and lower expression in Th-MYCN/Casp2−/− tumors." (PMID 30670683, 2019). "Repeated injection of FZD2 siRNA into NB xenografts significantly inhibited tumor growth in mice and led to decreased levels of β-catenin, MYCN and cyclin D1 protein." (PMID 31331081, 2019). "The category is based on age at diagnosis, INRG tumor stage, histologic category, grade of tumor differentiation, DNA ploidy, and copy number status at the MYCN oncogene locus and at chromosome 11q." (PMID 31500669, 2019). "A number of studies have demonstrated the potential to detect MNA in serum and plasma from patients with NB at diagnosis across all tumour stages using PCR methodology, thus raising the prospect of using MYCN as a circulating biomarker." (PMID 31088252, 2019). "More specifically, chromosomal region 2p15‐16 (XPO1/REL) was gained in a higher proportion of tumor cells than the 2p24 region (MYCN) in eight of the 48 patients (17%)." (PMID 31066214, 2019). "MYCN amplified NB1691‐Luc cells grew more rapidly and formed larger orthotopic tumours compared to non‐MYCN amplified SHSY5Y‐Luc cells consistent with MYCN amplified disease." (PMID 30536898, 2019). "Among them, genetic features such as the status of the v-myc avian myelocytomatosis viral oncogene neuroblastoma derived homolog (MYCN) gene, 11q23 allele status, and tumor ploidy are the most significant and clinically relevant factors." (PMID 31685009, 2019). "TBX2, which has thus far not been studied in NB, is most highly expressed in this tumor entity as compared to other tumor entities and also strongly upregulated in mouse neural crest-derived MYCN overexpressing NB46." (PMID 30451831, 2018). "In both in vitro and in vivo MYCN amplified models, treatment with these agents has been promising, inducing differentiation and apoptosis in cell lines and tumor growth suppression in xenografts." (PMID 30326621, 2018). "In one Dbh-MYCN tumor that harbors whole chromosome gains in chromosomes 3, 6 and 12, we observed a total of eight mutations of which one was a non-synonymous coding mutation." (PMID 29492199, 2018). "Although the other MYCN-amplified tumor sample NB2 showed low transcription levels of C2GNT1, we observed remarkable high levels of most of the downstream glycosyltransferases evaluated, suggesting a presumed high expression of Lewis glycans." (PMID 30344930, 2018). "The tumor had a highly rearranged genome with high-level focal amplifications of MYCN (319 CN; 660 FPKM), CCND2 (123 CN; FPKM 2516) and GLI2 (11 CN; FPKM 24)." (PMID 30262806, 2018).
tumor (continued). "In contrast to the increased DKK3 protein levels in murine tumour tissues, both p‐GSK3β and nuclear β‐catenin expression decreased after MYCN shRNA treatment." (PMID 29673070, 2018). "Overall, these data indicate that MRE11 is essential for proliferation and/or survival in MYCN-driven tumor cells." (PMID 30166519, 2018). "Similar results were obtained with patient-derived primary-tumor samples; while overexpression of ST3Gal3/6 was detected in one MYCN-amplified patient sample (NB1), overexpression of ST3Gal4 was found in the other (NB2)." (PMID 30344930, 2018). "The suppression of MYCN expression increased the levels of Bax and decreased the levels of Bcl‐2 and cyclin D1 proteins in cell‐derived tumour xenografts." (PMID 29673070, 2018). "MYCNOS-01 transcript levels were generally higher in NB and RMS tumor samples and cell lines with MYCN genomic amplification." (PMID 29466962, 2018). "The other tumor models have a higher average mutation burden of 3.89 (Th-MYCN), 5.5 (Dbh-MYCN) and 4.75 (ALK) mutations per exome and exhibit a longer average time to tumor formation." (PMID 29492199, 2018). "The following Model 2–4 show that DGscore remains highly significant after adjusting for tumor stage, MYCN amplification or age." (PMID 30012197, 2018). "ALK is almost exclusively co-amplified with MYCN, consistent with the proximity of these genes at 2p23-24 and therefore tumours harbouring ALK amplification tend to afford a poor prognosis." (PMID 29642598, 2018). "MYCN oncogene amplification has been recognized as the strongest indicator of aggressive tumor behavior for pNT patients." (PMID 29464082, 2018). "NB tumours expressing TrkB have a less favourable prognosis as the MYCN gene is amplified in this type of NB and also because TrkB ligands enhance viability, drug resistance and angiogenesis." (PMID 29315268, 2018). "High-risk NB patients are defined by having either metastatic disease diagnosed at an advanced age (> 18 months) or MYCN amplification in tumor." (PMID 29751783, 2018). "D04d and the matching tumor sample contained approximately 25–30 copies of MYCN as determined by SNP array." (PMID 28921546, 2018). "Among MYCN amplified High-MKI cases (n = 120), 101 (84.2%) tumors were MYCN protein (+), one (0.8%) tumor was MYC protein (+), 2 tumors (1.7%) were both proteins (+), and 16 tumors (13.3%) were both proteins (−)/(+/−)." (PMID 29464082, 2018). "This is of particular interest for a Myc driven tumor as both MYCN and C-Myc alter DNA damage responses, override cell cycle checkpoints, drive proliferation, and alter metabolic pathways." (PMID 29755654, 2018). "MYCN can down-regulate the epigenetically controlled miR-335, a tumour suppressor miRNA, leading to over-expression in target genes of the Transforming Growth Factor beta (TGF-β) non-canonical pathway, inhibiting both the migration and invasion of NB cells." (PMID 29315268, 2018). "In those two patients with MYCN amplification, the tumor recurred a short time after GTR, so chemotherapy was administered and one of the patients also underwent radiation therapy in accordance with high-risk protocols." (PMID 30245940, 2018). "In another study, lorlatinib was found to significantly reduce growth of tumours in the ALK F1174L/MYCN-driven genetically engineered mouse model of aggressive NB, which did not respond to crizotinib." (PMID 29642598, 2018). "A greater percentage of the tumour cells derived from MYCN shRNA‐treated mice exhibited characteristics of apoptosis, such as cell volume shrinkage, nuclear pyknosis and prominent apoptotic bodies." (PMID 29673070, 2018). "Currently, even more parameters are used for the classification of NBs, such as stage, age, histologic category, grade of tumor differentiation, the status of the MYCN oncogene, chromosome 11q status, and DNA ploidy." (PMID 29371588, 2018).
tumor (continued). "We did not detect gene amplifications in EGFR (n = 8) or Her2 (n = 16) by FISH and CISH, respectively; MYCN amplification was seen in one tumor using NGS." (PMID 29869738, 2018). "At the end of the 22 days, the tumour weights and the tumour volumes were significantly lower in the MYCN shRNA‐treated mice." (PMID 29673070, 2018). "Deregulation of mTOR expression is very common in tumor cells and it is targeted in many NB studies, as its inhibition destabilizes MYCN, reduces NB growth, and induces excessive autophagy activation that will result in the stimulation of cell death." (PMID 29371588, 2018). "Amplifications of the MYCN gene are known to be responsible for increased tumor growth, proliferation, and NB development 41,42." (PMID 29371588, 2018). "CBL0137 can downregulate FACT and MYCN expression and inhibit MYCN-driven tumor initiation and progression in MYCN mice and xenografts." (PMID 30581774, 2018). "Captivatingly, simultaneous overexpression of Survivin and oncogenic mycN generated tumors with shortened tumor latency, decreased apoptosis and displaying an increased frequency of structural chromosomal aberrations when compared to mycN-tumors." (PMID 29282022, 2017). "Patient age, tumor stage, histology, tumor grade, MYCN oncogene status, chromosome 11q status, and DNA ploidy have been reported to be the most clinically relevant prognostic factors in previous studies." (PMID 28465480, 2017). "Transcriptional targets of MYCN are also involved in many aspects of tumor biology, with dueling functions of unrestricted proliferation and cell death receptor activation." (PMID 29238067, 2017). "MYCN oncogene amplification is present in approximately 20% of NB patients and correlates with tumor progression, advanced disease stages and poor outcome." (PMID 28915622, 2017). "The down-regulation of the MYCN-miR17-92 network represents an interesting approach to inhibit uncontrolled cell proliferation and tumour growth in vivo." (PMID 29182544, 2017). "Our ddPCR protocol required only 2 ng of tumor DNA, and assessed MYCN copy number more precisely than FISH over a wide copy number range." (PMID 29156716, 2017). "Positive VEGF expression is significantly correlated with differentiated tumor histology and normal MYCN status, and hence predicts a favorable patient survival." (PMID 28894229, 2017). "Taken together, these results suggest that EWSR1 expression influences tumor progression in NB and is partially regulated by MYCN oncoprotein." (PMID 29212266, 2017). "Plasma-derived cfDNA also produced MYCN copy numbers that correlated well with those determined from tumor gDNA." (PMID 29156716, 2017). "Amplification of the MYCN proto-oncogene is a powerful prognostic indicator of advanced stages and rapid tumor progression." (PMID 28367105, 2017). "Intriguingly, simultaneous overexpression of Survivin and oncogenic mycN generated tumors with shortened tumor latency and significantly accelerated tumor growth, resulting in decreased survival time of mice when compared to U251-MGmycN/C tumors." (PMID 29282022, 2017). "What becomes immediately evident is that the MYCN-NA tumor side of the table has much higher F values and correspondingly lower p values." (PMID 28871274, 2017). "For this reason, we established tumor cell lines from spontaneous murine MYCN Tg tumors which were PTEN +/+ vs PTEN +/−in order to examine genetics of PTEN haploinsufficiency and AKT activation on tumor growth in a syngeneic genetic model." (PMID 28881723, 2017). "In summary, these results confirmed a positive correlation between VEGF expression and favorable biomarkers including CRT expression, differentiated tumor histology and unamplified MYCN." (PMID 28894229, 2017). "HUWE1 is an E3 ubiquitin ligase that controls the stability of MCL1, MYC and MYCN functions which would suggest a tumour‐suppressive role." (PMID 28003334, 2017).
tumor (continued). "In contrast, miR-9 is activated by MYCN and its amplification correlates with over expressed MYCN, advanced tumor grade and metastasis." (PMID 28358317, 2017). "We measured MYCN copy numbers in the range of 1.70 to 2.16 in tumor gDNA from patients 1–5 using ddPCR, which were in complete accordance with the diploid MYCN status determined by FISH." (PMID 29156716, 2017). "AHNAK was bound to MYCN in all conditions, and has been described as a tumour suppressor that can stimulate the growth suppressing functions of the TGF-β pathway." (PMID 28187790, 2017). "Inactivation of MYCN can lead to tumor regression through proliferation arrest and the induction of apoptosis." (PMID 28358317, 2017). "The results indicate that combination treatment of JQ1 and ABT-263 significantly inhibits tumor growth in MYCN-amplified SCLC xenografts." (PMID 29156797, 2017). "This revealed that cultured PDX cells at low (passage 3), middle (passage 15) and high (passage 30) passages retained the genomic aberration profiles (e.g. 1p deletion, MYCN amplification and 17q gain) observed in the corresponding patient tumor and xenograft." (PMID 28860499, 2017). "By contrast, MYCN amplified tumor samples have more NTN4 expression, which is in line with the expression data observed in NB cell lines analyzed in this work." (PMID 28038459, 2017). "The current results begin to define such characteristics of early p75 and HNK-1 expressing NCSC capable of tumor initiation by MYCN overexpression." (PMID 29238067, 2017). "One of the four MYCN‐amplified, high‐risk tumors, (UPENN‐RB‐175) was RB1+/+ and was diagnosed at 10 months, by which time the tumor had invaded both the retrolaminar portion of the optic nerve and showed massive choroidal invasion." (PMID 28211617, 2017). "MYCN copy number detection in tumor-derived cfDNA from plasma samples taken before and after surgery has been suggested as a useful evaluation step for surgery and neoadjuvant chemotherapy." (PMID 29156716, 2017). "Heterogeneity of MYCN has been documented recently to vary from tumor sites, during cancer progression and even following treatment." (PMID 28358317, 2017). "In terms of histological differentiation, 11 (92%) MYCN‐amplified tumors were poorly differentiated consisting of neuroblastic cells and few, if any rosettes; one tumor was described as mixed with respect to differentiation." (PMID 28211617, 2017). "Consistent with this, cell death ELISA and caspase 3 assays both showed that MYCN PTEN+/−neuroblastoma cells underwent less apoptosis as compared with MYCN PTEN+/+ tumor cells." (PMID 28881723, 2017). "MYCN copy numbers determined using plasma-derived cfDNA were distinctly higher than those determined from corresponding tumor gDNA for patients 1 and 4, respectively." (PMID 29156716, 2017). "Only one case had a different result, with the primary tumor sample showing MYCN amplification, but the BM cell sample showing normal signals." (PMID 28367105, 2017). "In the three tumor spheres formed from MYCN-amplified NB cell lines, CFC1 and the positive control CD133 were markedly increased and a quantitative PCR analysis confirmed the induction of CFC1." (PMID 28620148, 2017). "NDRG1 is one of the four members of the human NDRG family, and its designation comes from its expression being repressed by MYC and MYCN and its expression is negatively correlated with tumor progression in multiple neoplasms." (PMID 27894074, 2017). "Among the 10 amplification-based oncogenes, expression levels of MYC family genes, including MYC, MYCL, and MYCN, varied among tumor tissue samples." (PMID 28377632, 2017). "MYCN copy numbers detected by ddPCR were higher than the amplification levels determined by FISH for each tumor." (PMID 29156716, 2017).